NEDD4L (NEDD4 like E3 ubiquitin protein ligase)
Diseases named in the same sentence as NEDD4L in open-access papers (continued):
Sharing a sentence is not in itself a finding about the gene and the disease.
colitis (1 paper, 2024). Inflammation of the colon. "Cohousing eliminated the development of more severe DSS-induced colitis in Nedd4l-deficient mice compared with cohoused control littermates, indicating that NEDD4L protects against colitis in a manner dependent on the gut microbiota." (PMID 39688910, 2024). "Global KO of NEDD4L or its deficiency in IECs exacerbated colitis induced by dextran sulfate sodium (DSS) and 2,4,6-trinitrobenzene sulfonic acid (TNBS) and CRC induced by azoxymethane and DSS." (PMID 39688910, 2024). "Consistently, Nedd4l deficiency in IECs strongly exacerbated DSS/TNBS–induced colitis and AOM/DSS–induced CAC." (PMID 39688910, 2024). "NEDD4L deficiency in mice promoted colitis induced by dextran sulfate sodium (DSS) and 2,4,6-trinitrobenzene sulfonic acid (TNBS) and CRC induced by azoxymethane and DSS." (PMID 39688910, 2024). "In our study, Nedd4l global deficiency in mice exacerbated DSS-induced colitis in comparison with the WT mice." (PMID 39688910, 2024). "Further bone marrow chimera experiments demonstrated that Nedd4l deficiency in non–bone marrow cells aggravated DSS-induced colitis, suggesting an important role of NEDD4L in non–bone marrow cells." (PMID 39688910, 2024). "Importantly, ferroptosis inhibitors reduced the susceptibility of NEDD4L-deficient mice to colitis and colitis-associated CRC." (PMID 39688910, 2024). "Nedd4l deficiency in mice enhances sensitivity to experimental colitis." (PMID 39688910, 2024). "We then investigated whether Nedd4l deficiency might exacerbate colitis in an alternative model induced by TNBS." (PMID 39688910, 2024). "Additionally, Nedd4l deficiency in mice significantly promoted the pathogenesis of colitis and AOM/DSS–induced tumorigenesis." (PMID 39688910, 2024). "Nedd4l deficiency promotes colitis pathogenesis via ferroptosis in mice." (PMID 39688910, 2024). "To further evaluate whether the exacerbated colitis in Nedd4l-deficient mice compared with control littermates is microbiota dependent, we cohoused the Nedd4l-deficient mice with control littermates for 2 weeks before DSS administration." (PMID 39688910, 2024). "Collectively, our in vitro and in vivo data suggest that NEDD4L modulated SLC3A2 ubiquitinoylation to regulate DSS-induced colitis." (PMID 39688910, 2024). "Further analysis, including 16S rDNA sequencing of feces and in vivo supplementation of commensal intestinal bacteria, revealed that Lactobacillus and Bifidobacterium were critical for NEDD4L-regulated colitis." (PMID 39688910, 2024). "Remarkably, we observed more severe colitis after 3% DSS treatment in Nedd4l+/– mice compared with Nedd4l+/+ mice, as evidenced by significantly greater body weight loss, higher rectal bleeding score, and shorter colons in DSS-treated Nedd4l+/– mice." (PMID 39688910, 2024). "Collectively, these results suggest that the NEDD4L gene and protein were significantly inhibited in humans and mice with colitis, and NEDD4L expression was correlated with severity in patients with IBDs." (PMID 39688910, 2024). "Collectively, these data support the notion that Nedd4l deficiency in IECs contributed to both DSS-induced and TNBS-induced colonic damage and colitis." (PMID 39688910, 2024). "However, our data demonstrated that NEDD4L regulated DSS-induced colitis in an IL-17R signaling–independent manner." (PMID 39688910, 2024). "In our study, cohoused breeding of Nedd4l-deficient and WT mice developed comparable severities of DSS-induced colitis, suggesting that gut microbiota plays a pivotal role in NEDD4L-regulated colitis." (PMID 39688910, 2024). "SLC3A2 is a potential substrate of NEDD4L in DSS-induced colitis." (PMID 39688910, 2024). "Nedd4l deficiency in IECs exacerbates DSS-induced and TNBS-induced experimental colitis." (PMID 39688910, 2024). "The IL-17 neutralizing antibody treatment successfully inhibited DSS-mediated colitis in WT mice but did not eliminate the colitis phenotype difference induced by Nedd4l deficiency." (PMID 39688910, 2024).
colitis (continued). "Importantly, ferroptosis inhibitors, such as ferrostatin-1 and deferoxamine mesylate, reversed the colitis and CAC phenotype difference between WT and Nedd4l IEC-deficient (Nedd4lfl/flVillinCre) mice." (PMID 39688910, 2024). "The expression level of NEDD4L was negatively correlated with the disease status of colitis." (PMID 39688910, 2024). "Additionally, Nedd4l KO in mice significantly enhanced DSS/TNBS–induced colitis and AOM/DSS–induced CAC by triggering SLC3A2-mediated ferroptosis." (PMID 39688910, 2024). "Importantly, NEDD4L protein expression was lower in patients with moderate or severe colitis than in those with mild colitis from cohort 2, consistent with the GEO data, indicating that NEDD4L expression was negatively correlated with the severity of colitis." (PMID 39688910, 2024). "Furthermore, Nedd4l deficiency in IECs significantly impaired antimicrobial peptide expression in Nedd4lfl/fl VillinCre mice compared with Nedd4lfl/fl mice, suggesting that a much stronger impact, such as IEC death, plays a critical role during DSS-induced colitis." (PMID 39688910, 2024). "Here, we identified that both the gene and protein expression of NEDD4L was significantly inhibited in the IECs of patients with colitis and CRC, and negatively correlated with the disease status of colitis." (PMID 39688910, 2024). "In our study, we demonstrated that both the NEDD4L gene and protein were downregulated in IECs of patients with colitis or CAC, and this downregulation was correlated with the disease status of colitis and survival outcomes of CRC." (PMID 39688910, 2024). "Our study revealed a positive correlation between NEDD4L protein expression and SLC3A2 in humans with IBDs and CRC, demonstrating that the NEDD4L/SLC3A2/GPX4 axis played an important role in colitis and CAC." (PMID 39688910, 2024). "Mice reconstituted with Nedd4l deficiency in non-hematopoietic cells (WT→KO) exhibited a more severe colitis phenotype compared with the Nedd4l+/+ chimeras (WT→WT) following DSS treatment." (PMID 39688910, 2024). "The key cytokines involved in colitis, such as TNF-α, IL-17A, and IL-1α, were used to test whether DSS-induced downstream cytokines restricted NEDD4L expression." (PMID 39688910, 2024). "Based on the combined analysis of quantitative ubiquitination MS and interaction MS, we hypothesized that NEDD4L might interact with SLC3A2 and regulate its ubiquitination, triggering IEC ferroptosis and aggravating DSS-induced colitis." (PMID 39688910, 2024). "Collectively, these data implicate that NEDD4L in non-hematopoietic cells promoted the pathogenesis of DSS-induced colitis." (PMID 39688910, 2024). "Goblet cells are the most abundant cells in the intestine, and NEDD4L is highly expressed in goblet cells but downregulated in IECs of patients with IBDs; thus we employed Nedd4l IEC-KO mice to investigate the function of NEDD4L in IECs in colitis." (PMID 39688910, 2024). "Collectively, our data demonstrated that NEDD4L acted as an important regulator in IEC ferroptosis, thus maintaining intestinal homeostasis and controlling the development of colitis and CAC, suggesting that NEDD4L might be a potential target for the diagnosis and treatment of these diseases." (PMID 39688910, 2024). "To further explore whether the protective role of NEDD4L in colitis was intrinsic to IECs, we generated mice with IEC-specific KO of Nedd4l (Nedd4lfl/fl VillinCre) by crossing Nedd4l-floxed mice (Nedd4lfl/fl) with VillinCre mice, resulting in constitutive deletion of Nedd4l in the IECs." (PMID 39688910, 2024). "We had noticed that the expression of both the NEDD4L gene and protein was inhibited during the induction of colitis by DSS treatment in mice, indicating that DSS-induced IEC ferroptosis may be a potential inducer of the inhibition of NEDD4L expression during colitis." (PMID 39688910, 2024).
colitis (continued). "Although Syk is known to be a target for NEDD4L in mast cells, continual intraperitoneal (i.p.)injection of a Syk-specific inhibitor, BAY 61-3606, during colitis induction did not eliminate the colitis phenotype difference between Nedd4lfl/fl VillinCre and Nedd4lfl/fl mice." (PMID 39688910, 2024). "In contrast, other inhibitors related to signaling of potential targets of NEDD4L, such as BAY 61-3606 and anti–IL-17 neutralizing antibody, could not eliminate the phenotypic difference in DSS-induced colitis." (PMID 39688910, 2024).
Crohn disease (1 paper, 2024). A gastrointestinal disorder characterized by chronic inflammation involving all layers of the intestinal wall, noncaseating granulomas affecting the intestinal wall and regional lymph nodes, and transmural fibrosis. "NEDD4L expression was significantly inhibited in intestinal epithelial cells (IECs) of patients with Crohn’s disease, ulcerative colitis, and CRC." (PMID 39688910, 2024).
cutaneous melanoma (1 paper, 2024). A primary melanoma arising from atypical melanocytes in the skin. "For example, it is reported that the expression of NEDD4L was elevated in both cutaneous melanoma and lymph node metastatic melanoma compared to normal tissue." (PMID 39557844, 2024).
developmental delay (1 paper, 2012). "The NEDD4L gene is located on human chromosome 18q, which has long been investigated since partial deletions of the long arm of chromosome 18 lead to variable phenotypes, such as short height and developmental delay." (PMID 22957059, 2012).
diabetic angiopathy (1 paper, 2025). "However, the results from that study were dubious and not directly related to NEDD4L signaling since the authors used bioactive compounds to treat endothelial cells in a mouse model of diabetic angiopathy." (PMID 40136477, 2025).
diabetic cardiomyopathy (1 paper, 2022). Diabetic cardiomyopathy is a disorder of the heart muscle in people with diabetes. "The role of Nedd4L in the development of diabetic cardiomyopathy has also been explored in recent years." (PMID 35429991, 2022).
diverticulitis (1 paper, 2024). An infection that develops in the diverticula of the intestinal tract. "However, given the lack of clinical IBD biopsies from patients with infectious colitis or diverticulitis, we cannot conclude that NEDD4L expression would be inhibited in any inflammatory setting." (PMID 39688910, 2024).
HCMV infection (1 paper, 2019). "In addition to ITCH, UL42 interacted with Neural Precursor Cell Expressed, Developmentally Down-Regulated 4 (NEDD4)- family E3 ligases NEDD4 and NEDD4-like (NEDD4L), which were degraded during early HCMV infection." (PMID 31873071, 2019). "The third employed an unbiased global pulse-chase to compare the rates of protein degradation during HCMV infection against mock infection (NEDD4 and NEDD4L were not quantified in this latter screen)." (PMID 31873071, 2019).
intestinal tumour (1 paper, 2020). "Together, we conclude that loss of Nedd4 and Nedd4l in Apcmin animals promotes intestinal tumour progression by enhancing Wnt activation with increased numbers of ISCs and Paneth cells." (PMID 31867777, 2020).
ischemic stroke (1 paper, 2024). A stroke disorder caused by obstruction of blood flow to the brain, due to thrombotic (local blood clot formation) or embolic (due to a blood clot or other material traveling from another site) event. "The aim of this study was to investigate the impact of genetic ablation of NEDD4L on post-ischemic stroke outcomes." (PMID 38302612, 2024). "To confirm the presence of NEDD4L in cases of ischemic stroke, we initially established a mouse model of middle cerebral artery occlusion (MCAO) and subsequently verified the occurrence of ischemic damage." (PMID 38302612, 2024). "The E3 ubiquitin ligase NEDD4L has been shown to play a detrimental role in ischemic stroke injury." (PMID 38302612, 2024). "The heightened ferroptosis signaling observed with NEDD4L deletion suggests NEDD4L may play an inhibitory role in regulating ferroptosis after ischemic stroke." (PMID 38302612, 2024).
keloid (1 paper, 2022). An irregularly shaped, elevated mark on the skin caused by deposits of excessive amounts of collagen during wound healing. "We intersected DEGs in keloid samples and shBRCA1 normal DF samples and obtained 13 overlaps, including some well-known keloid or other fibrotic disease-related genes, such as COL11A1 and NEDD4L." (PMID 36015648, 2022).
kidney cancer (1 paper, 2021). Primary or metastatic malignant neoplasm involving the kidney. "Here, our results indicate that NEDD4L can also degrade ERBB3 in kidney cancer cells." (PMID 34539897, 2021).
lymphoma (1 paper, 2021). A malignant (clonal) proliferation of B- lymphocytes or T- lymphocytes which involves the lymph nodes, bone marrow and/or extranodal sites. "Nevertheless, the specific effect of NEDD4L on lymphoma has not been confirmed." (PMID 34869021, 2021).
nasopharyngeal carcinoma (1 paper, 2021). A carcinoma arising from the nasopharyngeal epithelium. "Further studies are needed to verify the function of NEDD4L in nasopharyngeal carcinoma." (PMID 34869021, 2021). "However, the mechanism of modulating EBV infection by NEDD4L and the role of NEDD4L in the initiation and progression of nasopharyngeal carcinoma are poorly understood." (PMID 34869021, 2021).
oral cancer (1 paper, 2024). "NEDD4L inhibits oral cancer proliferation by inducing ENO1 ubiquitination and degradation." (PMID 38520027, 2024).
pancreatic ductal adenocarcinoma (1 paper, 2020). An infiltrating adenocarcinoma that arises from the epithelial cells of the pancreas. "Furthermore, we observed significant inverse correlation between NEDD4L and ULK1 levels in the pancreatic regions from spontaneous pancreatic ductal adenocarcinoma (PDAC) mouse model driven by KrasLSL-G12D/+; Trp53LSL-R172H/+; Pdx1-Cre (KPC)." (PMID 31959741, 2020).
psoriasis (1 paper, 2024). An autoimmune condition characterized by red, well-delineated plaques with silvery scales that are usually on the extensor surfaces and scalp. "NEDD4L expression was reported to be downregulated in many tumors and psoriasis, suggesting a potential biomarker for diseases." (PMID 39688910, 2024).
rectal cancer (1 paper, 2021). A primary or metastatic malignant neoplasm that affects the rectum. "In addition, a study revealed that the expression of NEDD4L in rectal cancer patients was upregulated after radiotherapy, suggesting that NEDD4L might be helpful for the treatment of rectal cancer patients." (PMID 34869021, 2021).
sarcoma (1 paper, 2021). A usually aggressive malignant neoplasm of the soft tissue or bone. "Among the 33 cancer types in the TCGA database, there were four cancer types whose expression of NEDD4L protein can affect the overall survival of patients: KIRC, KIRP, LUAD, and sarcoma (SARC)." (PMID 34539897, 2021).
skin cancer (1 paper, 2021). "Future investigation is needed to elucidate the role of other pathways, including the TGF-β41 and PI3K/AKT42 pathways, in the function of NEDD4L in skin cancer." (PMID 33846348, 2021).
subependymal nodular heterotopia (1 paper, 2022). "Subependymal nodular heterotopias have been described in patients with chromosomal rearrangements, as well as associated with intragenic gene mutations (e.g., in FLNA, ARFGEF2, DCHS1, FAT4, ERMARD, and NEDD4L)." (PMID 35585091, 2022).
substance dependence (1 paper, 2021). The psychological or physiological need to take a substance in order to experience its effects or to avoid the effects of its absence. "Genes located in substance dependence, Signal transduction and also nervous functions pathways were down‐regulated: Cacna2d3, Epha6, Nedd4l and Vav2." (PMID 34196487, 2021). "Genes located in substance dependence, signal transduction and nervous functions pathways were down‐regulated: Cacna2d3, Epha6, Nedd4l and Vav2." (PMID 34196487, 2021).
triple-negative breast carcinoma (1 paper, 2024). An invasive breast carcinoma which is negative for expression of estrogen receptor (ER), progesterone receptor (PR), and human epidermal growth factor receptor 2 (HER2). "We then took a prospective validation approach using a novel target in triple negative breast cancer (TNBC), NEDD4L exon 13 (NEDD4Le13)." (PMID 38664594, 2024).